MT-TV (mitochondrially encoded tRNA-Val (GUN))
Synonyms: trnV; formerly MTTV
Gene: Mitochondrial transfer RNA gene on chromosome MT (1,602 to 1,670, forward strand). Ensembl gene ENSG00000210077.
Gene-disease validity (ClinGen):
ClinGen rates the evidence that MT-TV causes each of these diseases.
mitochondrial disease (mitochondrial): Definitive.
Leigh syndrome (mitochondrial): Moderate. A progressive neurological disease defined by specific neuropathological features associating brainstem and basal ganglia lesions.
Diseases named in the same sentence as MT-TV in open-access papers:
MT-TV is named in the same sentence as 1 disease in open-access papers, as found by Europe PMC text mining. Sharing a sentence is not in itself a finding about the gene and the disease. The quoted sentences say what the papers report.
tumor (1 paper, 2022). "Then, we investigated the expression level of MT-TV genes in tumor cells, and only tumor epithelial cells with MT-TV mutation (chrM:1670) showed increased expression of MT-TV." (PMID 35974387, 2022).